PARP1 (poly(ADP-ribose) polymerase 1)
Diseases named in the same sentence as PARP1 in open-access papers (continued):
Sharing a sentence is not in itself a finding about the gene and the disease.
cancer (continued). "Thus in cancer cells with BRCA2 mutation that already display a deficiency in DNA repair, inhibition of PARP1 activity leads to an accumulation of single strand breaks that are converted to double strand breaks that can not be repaired and result in cell death." (PMID 27488020, 2016). "Therefore, paradoxically, the expression of DDR molecules such as PARP1 and γH2AX could provide resistance to anti-cancer chemotherapy and radiation therapy, which induce cell death by causing DNA damage." (PMID 27643881, 2016). "However, PARP1 protein levels do not differ between isogenic pairs of HR deficient and proficient cancer cells." (PMID 27884198, 2016). "Berberine has been shown to induce apoptosis in cancer cells via various pathways such as activating the mitochondrial apoptotic pathway, regulating the activation of Bcl-2 family members as well as activating caspases and inducing the cleavage of poly (ADP-ribose) polymerase-1 (PARP-1)." (PMID 27338343, 2016). "Therefore, based on our findings, a combinatorial regimen targeting ATR and PARP1 pathways during NTP treatment might have the potential for development as an enhanced cancer therapy with favorable therapeutic responses." (PMID 27145275, 2016). "rs8689 is located at 5.3 kb upstream to 3′UTR region of PARP-1 and is in LD (r2 > 0.8) with PARP-1 SNPs rs2271347 (r2 = 1), rs61835377 (r2 = 1), rs1805403 (r2 = 1), and rs2793383 (r2 = 0.945), which has been shown to be associated with increased risk for several cancers and other diseases." (PMID 27746584, 2016). "As cancer cells deficient in ATR or DSB repair are sensitive to inhibitors of PARP1, we hypothesized that inhibition of ATR and PARP1 would result in more sensitization to the DSB inducing agent, irinotecan." (PMID 26257651, 2015). "Also known is that Snail can regulate cancer cell survival and that PARP-1 may be involved in its regulation." (PMID 25938539, 2015). "Therefore, all of these three molecules DNA-PKcs, PARP-1 and TNSK1BP1 are obviously implicated whether with the cancers prognosis or with the outcome of radio- or chemotherapy." (PMID 25749521, 2015). "However, PARP1 inhibition and the subsequent synthetic lethality can be used on other cancers that do not have mutations in BRCA1 or BRCA2 but that have a defect in the HR pathway, including mutations in ATM, Chk2, Rad51, and NBS1." (PMID 24795863, 2014). "Thus, PARP1 inhibitors should be reserved for clinical use when BRCA2 LOH can be verified in the tumour, assessment of which emerges as a critical requirement in the design of human clinical trials for the treatment of BRCA2‐deficient cancers." (PMID 24268522, 2014). "Thus, variations in PARP-1 gene may affect DNA repair in normal populations and facilitate cancer development in normal or exposed individuals." (PMID 24853559, 2014). "Furthermore, PARP-1 inhibition has emerged as a new therapeutic strategy for cancer." (PMID 23405229, 2013). "Therefore, strategies that target PAR metabolism for the improved treatment of cancer may be required to target PARP-1 and PARG individually in order to optimize cancer cell death." (PMID 23254695, 2013). "Thus, even though the PJ-34 effects are moderate in MDA-MB-231 cells, PARP-1 inhibitors could be efficiently combined with other anti-cancer drugs to enhance the efficacy of the treatment." (PMID 23405229, 2013). "By treating with PARP-1 inhibitors, one could reduce the inflammatory process, and thereby also decrease the induction of oxidative induced lesions (like OCDLs) that may lead to cancers." (PMID 24202328, 2013). "Moreover, there is a lack of specificity with respect to targeting cancer cells versus normal cells, unless the tumours have already been sensitised to PARP-1 inhibition due to a deficient DNA repair system or specific genetic background." (PMID 23405229, 2013).
cancer (continued). "Emerging literature, however, indicates other activities of PARP-1 that may explain the in vivo potency of some PARP-1 inhibitors that cannot be entirely attributed to their apparent in vitro activity and that could provide additional targets for anti-cancer therapies." (PMID 23785295, 2013). "This suggests that Erk may also regulate the PARP-1-dependent activation of NFκB, further points to a role for this interaction in cancer, as dysregulated Erk pathways are thought to be a present in an estimated one-third of cancers." (PMID 24202328, 2013). "For example, the finding that PARP1 is required to recruit certain RBPs to DNA damage sites implies that PARP1 inhibitors may be used to inhibit the RBP-dependent DNA-repair pathway for cancer treatment." (PMID 23921685, 2013). "As described in other cell models, we show that PARP1 inhibition triggers AKT activation but disclose the first insight on the role of PARP1/SIRT1 balancing in the control of the AKT/mTOR axis providing a further rationale for the treatment of this aggressive cancer." (PMID 23301673, 2013). "It is thus becoming increasingly apparent that a number of PARP-1-mediated cellular processes influence characteristics of tumor development, progression, and treatment response, including several of the eight “hallmarks of cancer” proposed by Hanahan and Weinberg." (PMID 24350055, 2013). "However, direct regulation of the mitotic checkpoint by PARP-1 is another important factor that may be targetable in cancer treatment." (PMID 24350055, 2013). "However, both of these cancer-associated polymorphic variants retained the ability to bind to PARP-1 (data not shown)." (PMID 23104860, 2012). "However, although the variant polymorphism was associated with reduced PARP-1 activity in normal cells, this was not the case in our panel of cancer cells." (PMID 19568233, 2009). "Our findings lead the path for creating novel inhibitors that can prevent TDP1 binding to PARP1 and consequently improve the clinical efficacy of the current TOP1 inhibitors for cancer treatment." (PMID 42187116, 2026). "The design, production, and study of new poly[ADP-ribose] polymerase 1 (PARP-1) inhibitors have emerged as an interesting exploration area, since PARP-1 is an overexpressed enzyme in several carcinomas." (PMID 41900056, 2026). "They compared the potency of exosomes derived from cancer and epithelial cells in targeting the delivery of CRISPR/Cas9 and downregulating the poly(ADP-ribose) polymerase-1 (PARP-1) expression." (PMID 40959562, 2025). "These drugs preferentially block the ability of PARP1 and PARP2 to initiate repair of DNA damage and selectively kill cancer cells that are unable to repair double strand breaks based on the concept of synthetic lethality." (PMID 40021124, 2025). "We found that across all 33 human cancer types, there is a positive correlation between HELLS and PARP1 mRNA expression, with the highest co-expression correlation in GBM, TGCT, OV, LUSC, BRCA, and CHOL." (PMID 41297801, 2025). "PARP1 plays a crucial role in homologous recombination (HR)-mediated DNA double-strand break (DSB) repair, which contributes to cancer cell survival in a sustained DNA damage environment." (PMID 40959108, 2025). "Several next-generation PARPis exhibited improved PARP1 selectivity over PARP2, resulting in lower hematological toxicity while demonstrating greater therapeutic efficacy in multiple cancer models." (PMID 40521389, 2025). "Given that PARP1 inhibitors, which target the SSB repair pathway, have been clinically approved for cancers with DNA repair defects, we further investigated the synergistic effect of ZFP36L1 overexpression with PARP1 inhibitors." (PMID 41285712, 2025).
cancer (continued). "Suppression of PCNA impaired Olaparib-induced overexpression of PARP1 and RAD51, thereby reversing the resistance of cancer cells to Olaparib." (PMID 40313621, 2025). "In a recent study, cancer cell-derived exosomes were used as natural carriers for CRISPR/Cas9 plasmid and single-guide RNA (sgRNA) targeting poly (ADP-ribose) polymerase-1 (PARP-1), a critical gene involved in DNA repair." (PMID 40284522, 2025). "The study highlights a multi-target mechanism, with strong interactions observed against key protein targets in cancer pathways, including HDM2, DNMT1, AKT2, and PARP-1." (PMID 40575462, 2025). "By inhibiting the active site of PARP1, these inhibitors effectively interfere with ADP-ribosylation function, rendering DNA damage in cancer cells irreparable, thereby inducing apoptosis." (PMID 41219748, 2025). "Among these shared targets, several key genes involved in cancer-related pathways were identified, including EGFR, PARP1, SRC, MET, GSK3B, and CYP19A1." (PMID 40963691, 2025). "PARP1 is overexpressed in some types of tumors, including CRC, where it regulates important hallmarks of cancer." (PMID 39858519, 2025). "It has been reported that PARP1 regulates BRD7 expression through PARylation-mediated ubiquitination, enhancing the survival of cancer cells." (PMID 40134437, 2025). "We also detected these cells’ response to replication stress and found that similar to human cancer cells, CHK1 activation was impaired in PARP1-K548R knock-in MEF cells compared with that in cells from WT mice." (PMID 38657044, 2024). "APEX1 promotes multidrug resistance in cancer, enhances KAT6A LLPS, and facilitates interaction between KAT6A and PARP1." (PMID 38973255, 2024). "Poly(ADP-ribose) polymerase-1 (PARP-1) is highly interesting as a potential biomarker and therapeutic target for cancer." (PMID 38451295, 2024). "However, PARP1 requires sufficient levels of NAD to function efficiently, and when NAD levels are low PARP1 can no longer perform its function which may result in missense variants being replicated that may lead to cancer." (PMID 38533302, 2024). "Both PARP1 and CtIP are important targets in cancer, so PACMP has the potential to become a high-value anti-cancer target." (PMID 39030557, 2024). "PARP-1 acts to repair DNA double-strand breaks through the microhomology-mediated end joint (MMEJ) pathway and is highly upregulated in the incidence of cancer." (PMID 38491556, 2024). "Specifically, PARP-1 is involved in base excision repair following SSBs and participates in alternative DNA repair processes such as NER, enhancing cancer cell resistance to radiation." (PMID 39655194, 2024). "Genes such as PARP1, NAMPT, AIMP2, MCL1, and TOMM20 exhibited widespread amplifications of CNVs in multiple cancers, while genes like RNF146, GPX4, ESR1, CUL4A, and PTEN showed widespread deletions." (PMID 38499384, 2024). "Considering that PARP1 participates in DNA repair, PARP inhibitors have been developed to suppress DNA repair and induce cell death in cancer cells." (PMID 38088577, 2024). "To further substantiate these findings, we sought to evaluate the effect that XRN2 depletion has on PARP1 activation in A549 and MDA-MB-231 cancer cells." (PMID 38339346, 2024). "However, it remains unclear how PARP1 trapping becomes impaired in cancer cells." (PMID 38973255, 2024). "Since PARP1 is an important gene in the BER pathway of DNA repair, and AIL suppresses cancer by inhibiting DNA repair." (PMID 38009603, 2024). "PARP1, PARG, ARH3, and AIF are among these pivotal molecules, which play critical roles in the control of cancer cell growth, progression, invasion, and metastasis." (PMID 38994937, 2024). "Nearly two decades ago, the discovery of the synthetic lethality interaction between two crucial DNA damage repair proteins, PARP1 and BRCA1/2, instigated cancer therapy with PARP inhibitors (PARPi), targeting tumors with high genomic instability." (PMID 39062190, 2024).
cancer (continued). "We further demonstrated that HBV-DNA-Pol increased PD-L1 expression by interfering with the nuclear translocation of PARP1, a negative regulator of STAT3-mediated PD-L1 transcription in various cancers, through interaction with PARP1." (PMID 38475878, 2024). "Rucaparib targets PARP1 to PARP4, while niraparib is designed to target PARP1 and PARP2 for cancer therapy." (PMID 39175540, 2024). "PARP-1 and HDAC2 were overexpressed in various cancers and contributed to tumor progression through their roles in DNA repair, transcriptional regulation, and the maintenance of genomic integrity." (PMID 39199199, 2024). "RBM14 is known to physically interact with PARP1, which is a key player in the DNA damage response (DDR) network and a target of cancer therapy." (PMID 38745208, 2024). "In accordance with their crucial role in the cell cycle and DNA repair and their overexpression in cancer cells, CDK-1 and PARP-1 were demonstrated to be key targets in BC progression." (PMID 37762072, 2023). "Increased sensitivity of cells with reduced PARP1 activity to the TOP1 inhibitor camptothecin, irinotecan and topotecan, which is used as a cancer therapeutic agent, raised a potential combinatorial treatment of TOP1i with PARPi." (PMID 37554969, 2023). "The genomic alterations of PDGFRA, PARP1, CREBL2, and DAB1 cooperatively contributed to the abnormality of cancer hallmarks." (PMID 37491836, 2023). "PARP1 and PARP2 have been extensively studied and well characterized for their role in DNA damage repair and cancer progression." (PMID 36814782, 2023). "Olaparib was the first FDA approved inhibitor of PARP1, and several derivates, along with new molecules, are now being investigated for treating BRCA-mutant cancer." (PMID 36678591, 2023). "Most of the current PARP inhibitors target either PARP1 and/or PARP2, and are highly effective against BRCA-mutant cancers but have significant side effects." (PMID 37667522, 2023). "We found that apoptosis-related genes URI1, PAK2, PARP1, CLU, and TIMP3 were significantly upregulated in multiple cell populations of cancer cells." (PMID 37124501, 2023). "DKC1 is targeted by PARP1 and C-MYC, which exert multiple biological functions and both show enormous prognostic value in a variety of cancers." (PMID 38082360, 2023). "Evidently, adavosertib can synergize with other cancer therapy agents that induce replication stress such as gemcitabine, CHK1, ATR, or PARP1 inhibitors, potentially by exacerbating replication stress to intolerable levels." (PMID 36632060, 2023). "ETV has the potential to be beneficial in treating various types of cancer, particularly due to its ability to inhibit KDM5B and potentially PARP-1 as well." (PMID 38004468, 2023). "Rucaparib is a PARP-1 inhibitor approved by the Food and Drug Administration (FDA) for cancer treatment in 2016." (PMID 37891641, 2023). "However, all genes associated with DNA repair or that can trigger synthetic lethality are not known, and identifying mutations in DNA damage response proteins and repair pathways may become one of the main criteria for selecting PARP1 inhibitors for cancer treatment." (PMID 38111536, 2023). "To further elaborate on apoptosis induction by KH16, we treated cancer cells and RPE1 cells with KH16 and probed for activated caspase-3 and the cleavage of its target PARP1." (PMID 37509312, 2023). "Although olaparib is a potent inhibitor of PARP1/2 enzyme activity (IC50 = 1 nM), this activity only translates to high micromolar cytotoxic activity (IC50>50 μM) in cancer cells." (PMID 37844763, 2023). "A recent study by Zhang and colleagues found that PACMP, a lncRNA-derived micropeptide, is an activator that promotes PARP1-meidiated PARylation, and PACMP inhibition renders sensitivity of cancer cells to diverse chemo- and targeted therapies." (PMID 36909172, 2023).
cancer (continued). "Veliparib is an oral potent inhibitor of PARP1/2 that has shown single-agent preclinical and clinical activity in several germline BRCA+ cancers, including breast and prostate cancer." (PMID 36975494, 2023). "In addition, similarly to PARP1 or DNA polymerase Polθ inhibitors that are used to treat HR-deficient cancers, the small molecule JE-RH-06 disrupts the interaction between the TLS polymerases REV1 and Polζ and shows preferential cytotoxicity in BRCA1-deficient cancer cells." (PMID 36749784, 2023). "Our proteomic profiling also identified poly(ADP-ribose) polymerase 1 (PARP1), the most abundant and active member of the PARP protein family and a major target for a class of anti-cancer therapies, as an early dynamic protein." (PMID 38012130, 2023). "The expression of genes involved in various pathways has changed in PARP1-KO cells, including DNA BER, transcriptional misregulation in cancer, the proteasome, and other processes." (PMID 36982223, 2023). "Inhibitors of tankyrases (the selective inhibitor STP1002 and the dual PARP1/PARP2 and TNKS1/TNKS2 inhibitor E7449), PARP7 (RBN-2397), and PARP14 (RBN-31430) are currently undergoing clinical trials for treatment of cancer and inflammatory diseases." (PMID 37832523, 2023). "Accordingly, we observe the upregulation of cleaved caspase-3, cleaved poly (ADP-ribose) polymerase-1 (PARP-1) and actin-related protein 2/3 (ARP2/3) in adjacent hepatocytes to cancer cell nests, while we notice a downregulation of E-cadherin." (PMID 35267627, 2022). "Amongst other enzymes, poly(ADP-ribose)-polymerase 1 (PARP1) was identified as a key player in this process, which resulted in the development of selective PARP inhibitors (PARPi) as anti-cancer drugs." (PMID 35267438, 2022). "Cancer research shows that sulforaphane treatment increases caspase-9 and poly-ADP ribose polymerase (PARP-1) activity, as well as cyclooxygenase IV (COX IV) activity, sensitizing cancer cells to mitochondria-mediated apoptosis." (PMID 36295538, 2022). "The MCODE analysis identified gene clusters for each cancer type with MYC, PCNA, PARP1, IDH1, FGF10, PTEN, and CCND1 as hub genes with high connectivity." (PMID 35001007, 2022). "Rucaparib (RCP) is a potent selective inhibitor of both PARP-1 and PARP-2 enzymes that induces synthetic lethality in cancer cells." (PMID 35236893, 2022). "PARP1 and RAD52 inhibitors are involved in the already known synthetic lethal mechanism in cancer treatment." (PMID 35741863, 2022). "When observing the levels of DNA repair marker PARP1 and DNA damage marker γ2HAX in lung NSC cancer MSCs, the SFPQ knock down reduced PARP1 and γ2HAX levels, but CD44v6 knockdown did not affect PARP1 and γ2HAX levels obviously." (PMID 35707369, 2022). "Poly(ADP-ribose) polymerase 1 (PARP1) participates in DNA damage repair to maintain genomic stability, and is overexpressed in human cancers to evade apoptosis." (PMID 35410300, 2022). "Recently we have shown that 7-MG inhibits DNA repair enzymes poly(ADP-ribose) polymerases, PARP1 and PARP2, in a competitive manner and accelerates apoptotic death of cancer cells induced by cisplatin and doxorubicin." (PMID 35873588, 2022). "Olaparib, which specifically inhibits PARP1 and PARP2 and thus is used for cancer therapy, also significantly suppressed cell proliferation at 5 μM and 10 μM." (PMID 35447104, 2022). "For example, exposure to alkylating agent MNNG and AG14361, a potential PARP1 inhibitor, was reported to significantly and durably increase phosphorylated AKT, leading to cancer cell growth recovery." (PMID 36203459, 2022). "In particular, alongside the traditional concept of targeting DDR enzymes such as PARP1, WEE1, and ATR, harnessing the epigenomic changes in cancer cells represents another exciting direction as DNA damage repair largely depends on chromatin configuration." (PMID 36123603, 2022).